GNE (glucosamine (UDP-N-acetyl)-2-epimerase/N-acetylmannosamine kinase)
Diseases named in the same sentence as GNE in open-access papers (continued):
Sharing a sentence is not in itself a finding about the gene and the disease.
cancer (7 papers, 2017 to 2024). A tumor composed of atypical neoplastic, often pleomorphic cells that invade other tissues. "Parental cancer cells as well as GNE-KO cells were able to generate MDSC-like cells with a strong suppressive phenotype." (PMID 38448555, 2024). "Meanwhile, further study should be focused on the mechanism of how low expressions of GNE regulate metastasis and the contradiction of hypersialylation mostly correlated with metastasis in cancers." (PMID 36429052, 2022). "Another gene that is duplicated in this region is GNE, which has been reported to be overexpressed in cancer (see Online Resource 1 for detailed information)." (PMID 32577795, 2020). "However, as the rate-limiting enzyme in the synthesis of CMP-Neu5Ac, GNE has been found to be down-regulated in several kinds of cancers." (PMID 36429052, 2022). "In addition, it was revealed that methylation of the GNE promoter triggers a decrease in GNE transcription levels in cancers and in HIV-infected lymphocytes." (PMID 36429052, 2022). "However, the role of GNE in cancer progression remains largely unclear." (PMID 36429052, 2022). "Interest in NAMPT as an anti-cancer target has led to the development of several NAMPT-specific inhibitors, including FK-866/APO-866, GNE-617, GNE-618, and CHS-828." (PMID 38424218, 2024). "Among the differentially expressed genes in primary samples, 7 of 39 genes (VHL, GNE, POLH, MAPK13, NOP14, INADL, CDC5L) were reported to be cancer-related in the literature." (PMID 28009993, 2017). "In particular, these ‘Compartment 1’ genes were expressed at comparable levels in the MCF10A cells and the cancer lines either with or without analog supplementation, with only the difference being slightly higher GNE transcription in the MCF10A cells." (PMID 29847599, 2018). "Thus, dysregulated miRNA-target gene pairs involved in these genes like miR-21/GNE, miR-369/TRIM2, and miR-203a/PDE7A might promote the migration of cancer cells." (PMID 30627543, 2018).
infection (4 papers, 2022 to 2025). The state of being infected such as from the introduction of a foreign agent such as serum, vaccine, antigenic substance or organism. "This lower recognition of GNe by pooled sera is possibly due to a lower immunogenicity of GNe during natural infection, as demonstrated by the low MFI signals obtained for GNe compared to the other two proteins in the triplex assay." (PMID 36815788, 2023). "Other factors such as animal age, phase of the infection, time between exposure or different localities, and different decay rates of the antibody responses could also explain the lower antibody response to GNe compared to GP38 and the N protein." (PMID 36815788, 2023). "A similar pattern of GNE expression was observed in MV1 cells, irrespective of infection with bovine- or mink-derived H5N1." (PMID 41157297, 2025).
genetic disorder (3 papers, 2014 to 2022). "Hereditary inclusion body myopathy 2 (HIBM2) (OMIM #600737) is a genetic disorder with autosomal recessive inheritance that is caused by mutations in the gene encoding UDP-acetylglucosamine 2-epimerase/N-acetylmannosamine kinase (GNE) on chromosome 9p13." (PMID 25126087, 2014).
kidney disease (2 papers, 2012 to 2023). "In this study, we examined the effect of hyposialylation caused by the GNE mutation on the renal disorders of the mt-mice, and attempted to suppress the renal disorders by administering 5-N-acetylneuraminic acid (Neu5Ac), a major sialic acid." (PMID 22253810, 2012). "We showed that the GNE V572L mt-mice had a shorter lifespan than wt- and ht-mice, and that they developed renal disorders with massive proteinuria shortly after birth." (PMID 22253810, 2012).
neuromuscular disease (2 papers, 2013 to 2021). "The findings of our study suggest that V727M GNE mutation may alter GNE and MYC protein interaction at the C terminal domain, thus could be leading to altered MYC role in regulating neuromuscular disease-associated gene expression, as well as the expression of ST genes in cells." (PMID 34825065, 2021).
metabolism disorders (1 paper, 2009). "Furthermore, the structure provides insights into the relationship between GNE mutations and GNE-related metabolism disorders." (PMID 19841673, 2009).
peripheral neuropathy (1 paper, 2024). A disorder affecting the peripheral nervous system. "Recently, several studies have reported peripheral neuropathy in affected persons with GNE mutations." (PMID 38674419, 2024). "This study was performed to find GNE mutations in six independent distal myopathy patients with or without peripheral neuropathy using whole-exome sequencing (WES)." (PMID 38674419, 2024). "This study was performed to find GNE mutations in distal myopathy patients with or without peripheral neuropathy using whole-exome sequencing (WES)." (PMID 38674419, 2024).
GNE also shares sentences with these, for which no sentence is quoted: autosomal recessive disease (2 papers); actin myopathy (1); adenocarcinoma (1); Adult onset (1); Alzheimer disease (1); axonal motor neuropathy (1); breast carcinoma (1); Calpainopathy (1); Cohen syndrome (1); developmental and epileptic encephalopathy (1); Dravet syndrome (1); Duchenne muscular dystrophy (1); Dysferlinopathy (1); epilepsy (1); Facioscapulohumeral dystrophy (1); glioblastoma (1); glioma (1); Intellectual disability (1); limb-girdle muscular dystrophy (1); lung adenocarcinoma (1); lymph node metastasis (1); melanoma (1); Miscarriage (1); muscle atrophy (1); Premature ovarian insufficiency (1); skeletal dysplasia (1); Splenomegaly (1); sporadic inclusion body myositis (1); tibial muscular dystrophy (1); vertebral anomaly (1).